DUBR (DPPA2 upstream binding RNA)
Synonyms: DUM; LINC00883; LINC0883
Gene: Long non-coding RNA gene on chromosome 3 (107,220,744 to 107,462,923, forward strand). Ensembl gene ENSG00000243701.
Diseases named in the same sentence as DUBR in open-access papers:
DUBR is named in the same sentence as 30 diseases in open-access papers, as found by Europe PMC text mining. Sharing a sentence is not in itself a finding about the gene and the disease. The quoted sentences say what the papers report.
lung adenocarcinoma (4 papers, 2021 to 2025). A carcinoma that arises from the lung and is characterized by the presence of malignant glandular epithelial cells. "Previous research has demonstrated that the expression of DUBR is down-regulated in lung adenocarcinoma and ovarian cancer, and that overexpression of DUBR hinders tumor progression 38,39." (PMID 37790850, 2023). "We also characterized the cell death phenotype resulting from DUBR knockdown in HCT116 human colon carcinoma cells, A549 lung adenocarcinoma cells and HEK-293 embryonic kidney cells, to expand our understanding of the role of DUBR in regulating survival in different human cell lines." (PMID 40117000, 2025).
breast carcinoma (1 paper, 2020). "Then, we selected 6 lncRNAs (MATN1-AS1, ENTPD3-AS1, DUBR, LINC00689, PSMA3-AS1 and LINC00482) through excluding the unannotated ones as well as those have been studied in breast cancer." (PMID 33054738, 2020).
colon adenocarcinoma (1 paper, 2025). "Analysis of the TCGA colon adenocarcinoma dataset accessed using OncoLnc shows that high expression of DUBR in patient tumors is predictive of poor patient survival." (PMID 40117000, 2025). "High expression levels of this ncRNA are predictive of poor patient outcome in colon adenocarcinoma, suggesting that DUBR may be involved in controlling cancer growth." (PMID 40117000, 2025).
colon carcinoma (1 paper, 2025). "We find that the human ncRNA DUBR is required for growth in the colon cancer cell line HCT116." (PMID 40117000, 2025). "Here we report that DUBR is a regulator of human colon cancer cell line HCT116 survival." (PMID 40117000, 2025). "In the human colon cancer cell line HCT116, each of the DUBR GapmeRs were able to significantly inhibit cell growth after 24-, 48- and 72-hour treatments." (PMID 40117000, 2025).
gastritis (1 paper, 2023). Inflammation of the stomach. "For GPX3, we predicted an upstream regulatory mechanism in GC, namely DUBR/hsa-miR-502-3p/GPX3 axis, which may play a role of inhibiting in malignant transformation from gastritis to GC and play a role of promoting cancer in stepwise tumor progression." (PMID 37790850, 2023).
hepatocellular carcinoma (1 paper, 2023). A malignant tumor that arises from hepatocytes. "Notably, the lncRNA DUBR, also known as linc00883, has been previously reported to be upregulated in hepatocellular carcinoma and has been found to contribute to oxaliplatin resistance." (PMID 37790850, 2023).
lung carcinoma (1 paper, 2024). "More recently, ZBTB11 was reported to participate in the long noncoding RNA (lncRNA) DUBR-mediated migration and invasion of lung cancer cells, suggesting a potential role of ZBTB11 during lung cancer progression." (PMID 38355937, 2024).
cancer (5 papers, 2018 to 2025). A tumor composed of atypical neoplastic, often pleomorphic cells that invade other tissues. "Then we measured the association of DUBR expression with cancer prognosis in these cancers." (PMID 34746238, 2021). "DUBR is a long non-coding RNA involved in several cancer types." (PMID 37701039, 2023). "Negligible research has been conducted to test the function of DUBR in cancer." (PMID 34746238, 2021). "However, whether DUBR promotes or suppresses cancer progression is controversial in different contexts." (PMID 37701039, 2023). "In conclusion, DUBR/miR-502-3p/GPX3 may be a potential regulatory pathway for normal gastric epithelium mucosa transforms into GC and tumor progression, which activates at different stages of tumor development to inhibit or promote cancer." (PMID 37790850, 2023).
tumor (2 papers, 2023 to 2025). "If similar interactions occur during human tumorigenesis, then RNA therapeutics targeting the release of DUBR-mediated silencing might potentially be explored as anti-tumor treatments." (PMID 40117000, 2025).
DUBR also shares sentences with these, for which no sentence is quoted: ovarian carcinoma (3 papers); gastric cancer (2); cervical squamous cell carcinoma (1); cholangiocarcinoma (1); endocervical adenocarcinoma (1); glioblastoma (1); glioma (1); head and neck squamous cell carcinoma (1); kidney chromophobe (1); lung squamous cell carcinoma (1); ovarian serous cystadenocarcinoma (1); pancreatic cancer (1); prostate adenocarcinoma (1); rectum adenocarcinoma (1); sarcoma (1); skin cutaneous melanoma (1); testicular germ cell tumor (1); thymoma (1); thyroid carcinoma (1); uterine carcinosarcoma (1); uterine corpus endometrial carcinoma (1).